SNHG1 (small nucleolar RNA host gene 1)
Diseases named in the same sentence as SNHG1 in open-access papers (continued):
Sharing a sentence is not in itself a finding about the gene and the disease.
acute myeloid leukemia (7 papers, 2019 to 2024). Acute myeloid leukemia (AML) is a group of neoplasms arising from precursor cells committed to the myeloid cell-line differentiation. "Overexpression of SNHG1 facilitates the proliferation via miR-488-5p/NUP205 pathway in acute myeloid leukemia cells." (PMID 32536864, 2020). "In acute myeloid leukemia (AML), extracellular lncRNAs LINC00265, LINC00467, UCA1, and SNHG1 are promising biomarkers for disease diagnosis and treatment monitoring." (PMID 39886670, 2024).
ovarian carcinoma (7 papers, 2020 to 2025). A malignant neoplasm originating from the surface ovarian epithelium. "Among these SNHGs, SNHG1 play a critical role in many malignant tumors, including colon cancer, ovarian cancer, pancreatic cancer, glioma, and lung cancer, via multiple pathways and mechanisms." (PMID 41200835, 2025). "SNHG1 also facilitated proliferation and metastasis of Ovarian Cancer (OC) by activating Akt signaling pathway." (PMID 36087568, 2022). "Most importantly, the study confirmed that lnc-SNHG1 functioned as a ceRNA with miR-216b-5p, which was critical in modulating paclitaxel sensitivity of ovarian cancer cells." (PMID 33302997, 2020). "Lnc-SNHG1 functioned as a ceRNA with miR-216b-5p, which was critical in modulating the paclitaxel sensitivity of ovarian cancer cells." (PMID 33302997, 2020). "To our knowledge, we for the first time claimed that lnc-SNHG1 by sponging miR-216b-5p might contribute to the paclitaxel resistance in ovarian cancer cells." (PMID 33302997, 2020). "This study further explored whether lnc-SNHG1 bound to miR-216b-5p to affect the paclitaxel sensitivity of ovarian cancer cells." (PMID 33302997, 2020). "The present study explored whether lnc-SNHG1 bound to miR-216b-5p to affect the paclitaxel sensitivity of ovarian cancer cells." (PMID 33302997, 2020). "Recent study showed that SNHG1 and SNHG16 can regulate the activity of matrix metalloproteinases (MMPs) to promote EMT, and then influence the invasion and migration abilities of ovarian cancer cells." (PMID 41200835, 2025). "By searching related literature and databases, about 30% lncRNAs have been verified to play roles in the regulation of proliferation, invasion, and migration of ovarian cancer cells, including ZFAS1, SNHG1, GAS5, EMX20S, GIHCG, TP53TG1, EPB41L4A-AS1, SNHG8, SNHG6, and HCP5." (PMID 33519912, 2020). "Whether lnc-SNHG1 is overexpressed in patients with chemoresistant ovarian cancer has not been reported." (PMID 33302997, 2020).
cholangiocarcinoma (6 papers, 2019 to 2024). A carcinoma that arises from the intrahepatic biliary tree (intrahepatic cholangiocarcinoma) or from the junction, or adjacent to the junction, of the right and left hepatic ducts (hilar cholangiocarcinoma). "The small nucleolar RNA host gene 1 (SNHG1)/miR-140/TLR4/NF-κB signaling axis plays a crucial role in cholangiocarcinoma tumorigenesis and progression." (PMID 33083486, 2020). "By regulating the transcription of CDKN1A epigenetically in the nucleus, lncRNA SNHG1 is likely to promote malignancy of cholangiocarcinoma." (PMID 32851072, 2020). "Upregulated SNHG1 could promote cholangiocarcinoma cell proliferation, migration, and cell cycle but reduce apoptosis, and the interaction between SNHG1 and EZH2 could target CDKN1A to promote the biological behavior of cholangiocarcinoma." (PMID 31691514, 2019). "Li found SNHG1, a long non-coding RNA, acting as a ceRNA (competing endogenous RNA) for miR-140, promotes the expression of TLR4 and activates the NF-ĸB signaling pathway, thus regulating the growth and tumorigenesis of cholangiocarcinoma." (PMID 38577599, 2024).
esophageal squamous cell carcinoma (5 papers, 2022 to 2025). Esophageal squamous cell carcinoma (ESCC) is a type of esophageal carcinoma (EC) that can affect any part of the esophagus, but is usually located in the upper or middle third. "For example, prior research showed that SNHG1 could bind to miR-204 to inhibit it, thus promoting migratory, and invasive abilities but repressing apoptosis in esophageal squamous cell cancer." (PMID 36230661, 2022). "Studies have documented that lncRNA SNHG1 is significantly upregulated in the cells and tissues of esophageal squamous cell carcinoma (ESCC) compared with neighboring noncancerous tissues." (PMID 37684619, 2023).
myocardial infarction (5 papers, 2021 to 2023). Gross necrosis of the myocardium, as a result of interruption of the blood supply to the area, as in coronary thrombosis. "For example, in the treatment of myocardial infarction, a positive feedback loop between SNHG1 and c-Myc is involved in the treatment of heart failure after myocardial infarction." (PMID 37684619, 2023). "SNHG1 was found to be involved in cardiac regeneration and repair after myocardial infarction by activating the PTEN/PI3K/AKT pathway and leading to continuous cell cycle re-entry." (PMID 37013574, 2023). "In the heart, Myc is also engaged in a positive feedback loop with the lncRNA small nucleolar RNA host gene 1 Snhg1 (Snhg1), promoting cardiomyocytes’ proliferation and regeneration upon both myocardial infarction and ischemia/reperfusion, with reduced CMs’ apoptosis and size of the infarcted area." (PMID 37606389, 2023). "Overexpression of Snhg1 promoted CM proliferation, angiogenesis, and inhibited CM apoptosis after myocardial infarction, which further improved post-MI cardiac function." (PMID 34646377, 2021). "Besides, lncRNA small nucleolar RNA host gene 1 (Snhg1) exerts anti-apoptotic effects on cardiomyocyte and myocardial infarction (MI) heart, by activating the PI3K/AKT/c-Myc pathway, which in turn enhances the expression of Snhg1, thus forming a positive feedback loop." (PMID 35990951, 2022).
nasopharyngeal carcinoma (5 papers, 2019 to 2021). A carcinoma arising from the nasopharyngeal epithelium. "Transfection was conducted to construct nasopharyngeal carcinoma cells with different expressions of SNHG1, miR‐145‐5p and NUAK1." (PMID 29575772, 2019). "SNHG1 is highly expressed in nasopharyngeal carcinoma tissues and in cell lines." (PMID 29575772, 2019). "SNHG1 can also activate the expression of NUAK1 by downregulating miR-145-5p and thus induce epithelial-mesenchymal transition in nasopharyngeal carcinoma cells." (PMID 32497022, 2020).
osteoporosis (5 papers, 2019 to 2023). A condition of reduced bone mass, with decreased cortical thickness and a decrease in the number and size of the trabeculae of cancellous bone (but normal chemical composition), resulting in increased fracture incidence. "In this study, we aimed to elucidate the role of lncRNA SNHG1 and its associated pathway on the differentiation of BMSCs in osteoporosis." (PMID 34854215, 2022). "Therefore, the down-regulated SNHG1 after menopause and during the development of osteoporosis may be also caused by the changed levels of hormones." (PMID 31693735, 2019). "We constructed the NEAT1-hsa-miR-128-3p-IL17RA and SNHG1-hsa-miR-128-3p-IL17RA networks to provide a theoretical basis for understanding the molecular mechanisms of IL17RA involvement in osteoporosis." (PMID 37600656, 2023). "This study provides additional insights into the molecular mechanisms of the lncRNA SNHG1/PTBPT1/DNMT1/Opg pathway in the pathogenesis of osteoporosis and presents novel ideas for developing new prevention and treatment measures for osteoporosis." (PMID 34854215, 2022). "Emerging evidences showed that SNHG1 is correlated with the development and progression of osteoporosis." (PMID 34732133, 2021). "Compared with healthy postmenopausal women, postmenopausal women with osteoporosis had lower plasma levels of SNHG1 in a 6-year follow-up study." (PMID 32664424, 2020). "In conclusion, plasma levels of SNHG1 were reduced with menopause and the development of osteoporosis." (PMID 31693735, 2019). "Our study observed that plasma levels of SNHG1 at 12 months before diagnosis was sufficient to distinguish postmenopausal osteoporosis patients from healthy controls." (PMID 31693735, 2019). "In the present study we observed that plasma SNHG1 was down-regulated with menopause and the development of osteoporosis." (PMID 31693735, 2019). "Compared with the pre-treatment levels of plasma SNHG1, plasma levels of SNHG1 were significantly increased in the 76 postmenopausal osteoporosis patients at 3 months (post-treatment) after the beginning of treatment (P<0.05)." (PMID 31693735, 2019). "We, in the present study, first showed that SNHG1 was down-regulated with menopause and the development of osteoporosis, and plasma SNHG1 showed predictive values for postmenopausal osteoporosis." (PMID 31693735, 2019). "NEAT1 and SNHG1 are thus promising targets for the treatment of osteoporosis." (PMID 37600656, 2023). "In summary, our findings identified that lncRNA SNHG1 regulated by SP1 play a promoting role in osteoporosis development that suppressing osteogenic differentiation and angiogenesis but facilitating osteoclast differentiation by modulating SFRP1-mediated Wnt signaling through sponging miR-181c-5p." (PMID 34732133, 2021). "From these findings, it could elucidate that miR-181c-5p is a functional target downstream of SNHG1 in osteoporosis." (PMID 34732133, 2021). "Although SNHG1 is well-established in cancer biology as a regulator of cancer cell behavior, the molecular mechanism of SNHG1 in osteoporosis is still unknown." (PMID 32664424, 2020). "lncRNA SNHG1 (small nucleolar RNA host gene 1) has been found to be downregulated in osteoporosis." (PMID 32664424, 2020). "Thus, we conclude that SNHG1 plays a role in the osteoporotic changes in the in vivo model of osteoporosis, which may be mediated by Opg." (PMID 34854215, 2022). "Further, SNHG1 silence might provide a potential treatment for osteoporosis." (PMID 34732133, 2021). "It is worth to explore whether SP1 can affect the progression of osteoporosis by modulating SNHG1." (PMID 34732133, 2021). "Therefore, menopause may mediate the down-regulation of SNHG1, which contributes to the development of osteoporosis." (PMID 31693735, 2019). "SNHG1 expression is up-regulated in OVX mice, which inhibits osteoblast differentiation and angiogenesis while promoting osteoclast formation, leading to osteoporosis." (PMID 37600656, 2023).
osteoporosis (continued). "In the present study, lncRNA SNHG1 was found to enhance BMSC adipogenic differentiation but inhibit BMSC osteogenic differentiation, implicating its role in osteoporosis." (PMID 34854215, 2022). "Therefore, SNHG1 may interact with these miRNAs to participate in osteoporosis." (PMID 31693735, 2019). "Therefore, SNHG1 may be involved in the development of osteoporosis." (PMID 31693735, 2019). "RT-qPCR was performed to investigate the differential expression of SNHG1 in the 122 healthy premenopausal females (HPRE group), 76 postmenopausal osteoporosis patients (POSTO group), and 202 healthy postmenopausal females (HPOST group)." (PMID 31693735, 2019). "Additionally, MicroCT (or μCT) analysis was not performed to support the function of SNHG1 in osteoporosis." (PMID 34854215, 2022). "Therefore, we hypothesized that lncRNA SNHG1 could regulate the expression of DNMT1 and subsequently influence Opg methylation status, contributing to the occurrence of osteoporosis, but it needs further determination." (PMID 34854215, 2022).
rectal cancer (5 papers, 2020 to 2025). A primary or metastatic malignant neoplasm that affects the rectum. "Based on network modeling, lncRNA KCNQ1OT1 (AUC>0.85) and SNHG1 (AUC>0.94) were unveiled as common diagnostic biomarkers for the initiation and metastasis of colon and rectal cancers." (PMID 33194594, 2020). "Especially, the KCNQ1OT1 and SNHG1 were unveiled as common lncRNA biomarkers with critical roles in the initiation and metastasis of colon and rectal cancers via distinct ceRNA mechanisms." (PMID 33194594, 2020). "In particular, KCNQ1OT1 and SNHG1 function in colon and rectal cancers via different ceRNA mechanisms." (PMID 33194594, 2020). "Comparatively, SNHG1 was found to promote initiation and metastasis of rectal cancer through regulating let-7b-5p/ATP6V1F and miR-423-5p/EZH2 axes, respectively." (PMID 33194594, 2020). "LncRNA KCNQ1OT1 and SNHG1 may contribute to the progression of colon and rectal cancers through distinct mechanisms." (PMID 33194594, 2020). "Based on our computational model, KCNQ1OT1 and SNHG1 possessing hub nodes properties in all of the four context-specific ceRNA networks, were identified as shared lncRNA biomarkers in colon and rectal cancer, revealing their critical role in colorectal carcinogenesis." (PMID 33194594, 2020). "The SNHG1 ceRNA network is common for all CRC sites, but only interacts with RFWD3 and E2F8 in the rectum, indicating a potential role for this network in rectum cancer." (PMID 34178670, 2021). "As an interesting result, we found that KCNQ1OT1 and SNHG1 could regulate the initiation and metastasis of colon and rectal cancers through distinct ceRNA regulatory axes, which have not been reported in previous studies." (PMID 33194594, 2020).
breast tumor (4 papers, 2015 to 2023). "Suppression of SNHG1 expression inhibited the cell proliferation and migration, while induced G2/M arrest in breast tumor cells." (PMID 36597150, 2023). "It has been shown that there were Small Nucleolar RNA Host Gene 1 (SNHG1) up regulations in breast tumor tissues and cell lines." (PMID 36597150, 2023). "SNHG1 sponged miR-573 to elevate the expression level of LMO4 in the breast tumor cells." (PMID 36597150, 2023). "In addition, SNHG1 downregulation inhibited breast tumor growth in vivo." (PMID 34806925, 2021). "The regulatory role of sno-miR-28 is further confirmed by our expression profiling studies which relate SNHG1, SNORD28 and sno-miR-28 to breast tumours." (PMID 26061048, 2015). "In addition, SNHG1, SNORD28 and sno-miR-28 are all significantly upregulated in breast tumours and the overexpression of sno-miR-28 promotes breast epithelial cell proliferation." (PMID 26061048, 2015). "To further investigate, in a cohort of 26 pairs of matched malignant and non-malignant breast tissues samples, we found that SNHG1, SNORD28 and sno-miR-28 were all significantly upregulated in breast tumours." (PMID 26061048, 2015).
lung squamous cell carcinoma (4 papers, 2017 to 2020). "In addition, SNHG1 plays an oncogenic role in lung squamous cell carcinoma through ZEB1 signaling pathway by inhibiting TAp63." (PMID 29872497, 2018). "Our findings showed that SNHG1 was higher expression in tumor tissues compared to normal tissues in lung adenocarcinoma (LUAD) and lung squamous cell carcinoma (LUSC) (P < 0.05)." (PMID 28147312, 2017).
meningioma (4 papers, 2020 to 2023). A generally slow growing tumor attached to the dura mater. "The long non-coding (lnc) RNA SNHG1 was found to inhibit apoptosis in BEN-1-1 and IOMM-Lee cells, and SNHG1 deficiency restrains cell growth and accelerates apoptosis in meningioma cell lines via the Wnt pathway." (PMID 35712491, 2022). "In fact, the SNHG1/miR-556-5p/TCF12 axis could promote the proliferation of meningioma cells and suppress their apoptosis by enhancing the activity of Wnt signaling." (PMID 34885097, 2021). "Meanwhile, SNHG1, LINC00702, LINC00460, and MEG3 have been found to partake in the pathogenesis of meningioma." (PMID 34885097, 2021).
Alzheimer disease (2 papers, 2021 to 2023). A progressive, neurodegenerative disease characterized by loss of function and death of nerve cells in several areas of the brain leading to loss of cognitive function such as memory and language. "SNHG1 is a recently described lncRNA involved in the development of several tumors and other types of disorders, including Alzheimer’s disease (AD) and Parkinson’s disease (PD)." (PMID 34956196, 2021). "Our findings are also in agreement with reports concerning upregulation of SNHG1 in other neurological disorders such as in vitro cell models of Parkinson’s disease (PD) and Alzheimer’s disease (AD), a mouse model of PD, and human postmortem brain tissue samples derived from PD patients." (PMID 37189549, 2023).
Cirrhosis (2 papers, 2022 to 2024). A chronic disorder of the liver in which liver tissue becomes scarred and is partially replaced by regenerative nodules and fibrotic tissue resulting in loss of liver function. "Silencing of SNHG1 significantly ameliorates cirrhosis in livers of mice, while miR-15a mimic treatment in BMSCs restrains cirrhosis in mice, suggesting that SNHG1 silencing alleviates cirrhosis via the miR-15a/SMURF1 axis." (PMID 39200161, 2024). "Next, our focus was shifted to the role of the lncRNA SNHG1/miR-15a/SMURF1 axis in cirrhosis in mice." (PMID 35194023, 2022). "Therefore, our work was designed to figure out impacts of lncRNA SNHG1 on cirrhosis by orchestrating HLC differentiation of BMSCs via miR-15a/SMURF1/UVRAG/ATG5/Wnt5a axis." (PMID 35194023, 2022). "Therefore, lncRNA SNHG1 silencing might be involved in the protective role of BMSCs against cirrhosis." (PMID 35194023, 2022). "Consistently, our work found that lncRNA SNHG1 repressed HLC differentiation of BMSCs in vitro and augmented liver fibrosis in mice with cirrhosis by binding to miR-15a." (PMID 35194023, 2022). "HGF-induced BMSCs with manipulated SNHG1/miR-15a/SMURF1 expression, after 7-d culture in vitro, were injected into mice to observe their effects on cirrhosis in mice." (PMID 35194023, 2022). "Long noncoding RNA (lncRNA) SNHG1 has been demonstrated to orchestrate BMSC differentiation, whereas its role in cirrhosis remains elusive." (PMID 35194023, 2022). "Conclusively, lncRNA SNHG1 silencing might facilitate HLC differentiation from mouse BMSCs and alleviate cirrhosis via the miR-15a/SMURF1/UVRAG/ATG5/Wnt5a axis." (PMID 35194023, 2022). "Briefly, lncRNA SNHG1 silencing was observed to downregulate SMURF1 by upregulating miR-15a, diminishing ubiquitination of UVRAG to activate ATG5/Wnt5a axis, which accelerated HLC differentiation from BMSCs and repressed liver fibrosis to inhibit cirrhosis." (PMID 35194023, 2022). "In addition, we observed little therapeutic effect on cirrhosis of tail vein injection of untreated BMSCs, whereas obvious alleviation of cirrhosis was witnessed after injection of HGF-induced BMSCs, while this effect was enhanced by silencing of lncRNA SNHG1 in the cells." (PMID 35194023, 2022).
dysplasia (2 papers, 2020 to 2025). A usually neoplastic transformation of the cell, associated with altered architectural tissue patterns. "Additionally, SNHG1 expression was significantly elevated in patients who progressed to low- or high-grade dysplasia, as confirmed by diagnostic endoscopic biopsies." (PMID 40629071, 2025). "First, they suggest that SNHG1 could serve as a predictive biomarker for BE progression, particularly in identifying patients at risk for dysplasia following RFA treatment." (PMID 40629071, 2025). "In summary, this section identifies SNHG1 as a clinically and mechanistically relevant lncRNA that modulates the interaction between ULK1 and Notch1, and is significantly upregulated in BE patients who later developed dysplasia." (PMID 40629071, 2025).
glioblastoma (2 papers, 2017 to 2022). The most malignant astrocytic tumor (WHO grade IV). "Taking glioblastoma multiforme as a case study, we identified a candidate lncRNA gene SNHG1 as a novel disease risk factor for disease diagnosis and prognosis." (PMID 28076842, 2017).
laryngeal squamous cell carcinoma (2 papers, 2019 to 2022). A squamous cell carcinoma that arises from the larynx. "Particularly, SNHG1 is involved in the regulation of oral squamous cell carcinoma, laryngeal squamous cell carcinoma, and esophageal squamous cell cancer." (PMID 35836822, 2022). "Knockdown of SNHG1 inhibited cell proliferation, migration, and invasion but promoted cell apoptosis in laryngeal squamous cell carcinoma." (PMID 35836822, 2022).